5_8S_rRNA (5.8S ribosomal RNA )
Synonyms: RNA5-8SP; LOC110467520
Gene: Ribosomal RNA gene on chromosome 22 (11,249,809 to 11,249,959, reverse strand). Ensembl gene ENSG00000276871.
Gene Ontology:
Molecular function: structural constituent of ribosome
Cellular component: ribosome
Homologues: Orthologues: chimpanzee 5_8S_rRNA (95% identical), zebrafish 5_8S_rRNA (88% identical), zebrafish si:dkeyp-3b12.15 (88% identical), zebrafish 5_8S_rRNA (87% identical), rat 5_8S_rRNA (86% identical), rat 5_8S_rRNA (85% identical), rat 5_8S_rRNA (84% identical), rat 5_8S_rRNA (83% identical), rat 5_8S_rRNA (82% identical), rat 5_8S_rRNA (81% identical), mouse Gm54867 (81% identical), mouse Gm55073 (72% identical). Paralogues in human: 5_8S_rRNA (99% identical), 5_8S_rRNA (94% identical), 5_8S_rRNA (91% identical), RNA5-8SN1 (91% identical), RNA5-8SN2 (91% identical), RNA5-8SN3 (91% identical), RNA5-8SN4 (91% identical), RNA5-8SN5 (91% identical), 5_8S_rRNA (87% identical), 5_8S_rRNA (86% identical).